CLEC1B (C-type lectin domain family 1 member B)
Description:
C-type lectin-like receptor that serves as a platelet receptor for the lymphatic endothelial marker PDPN. Plays an essential role in blood/lymphatic vessel separation and thrombus formation through homophilic association. Acts as a negative regulator of lymphatic endothelial cell behavior by inhibiting proliferation, migration, and tube formation. Upon ligand binding, triggers a signaling cascade via sequential activation of SRC and SYK tyrosine kinases, leading to activation of PLCG2. Through this pathway, mediates platelet adhesion, aggregation, and secretion in response to PDPN-expressing cells. During embryonic development, plays a central role in cerebrovascular formation and blood/lymphatic vessel separation. Interacts with PDPN on neuroepithelial cells to promote platelet activation, thereby ensuring maturation and integrity of cerebrovascular structures and preventing hemorrhage. (Microbial infection) Acts as a receptor for the platelet-aggregating snake venom protein rhodocytin. Rhodocytin binding leads to tyrosine phosphorylation and this promotes the binding of spleen tyrosine kinase (SYK) and initiation of downstream tyrosine phosphorylation events and activation of PLCG2. (Microbial infection) Acts as an attachment factor for Human immunodeficiency virus type 1 (HIV-1) and facilitates its capture by platelets.
Synonyms: CLEC-2; CLEC2; 1810061I13Rik; PRO1384; QDED721
Tractability: Antibody: its Gene Ontology location is reachable by antibodies, with high confidence; UniProt predicts a signal peptide or a membrane-spanning region.
Gene: Protein-coding gene on chromosome 12 (9,985,642 to 10,013,424, reverse strand). Ensembl gene ENSG00000165682.
Subcellular location: Membrane
Pathways (Reactome):
Cellular responses to stimuli: Heme signaling
Hemostasis: GPVI-mediated activation cascade
Gene Ontology:
Molecular function: protein binding; transmembrane signaling receptor activity
Biological process: signal transduction; cell surface receptor signaling pathway; defense response; platelet formation
Cellular component: plasma membrane; cell surface; membrane
Genetic constraint (gnomAD): Loss-of-function variants: 27 observed, 25.08 expected, observed/expected ratio (o/e) 1.08, 90% interval 0.79 to 1.48. The upper end of that interval is the gene's LOEUF score, 1.48, which puts it in group 6 of 6, group 1 being the genes least tolerant of losing a copy. Missense variants: 275 observed, 269.06 expected, observed/expected ratio (o/e) 1.02, 90% interval 0.93 to 1.13. Synonymous variants: 105 observed, 92.25 expected, observed/expected ratio (o/e) 1.14, 90% interval 0.97 to 1.34.
Homologues: Orthologues: chimpanzee CLEC1B (96% identical), macaque CLEC1B (93% identical), pig CLEC1B (69% identical), guinea pig CLEC1B (66% identical), mouse Clec1b (64% identical), rat Clec1b (59% identical), zebrafish si:ch211-170d8.8 (17% identical), zebrafish si:dkey-26c10.5 (17% identical), zebrafish si:ch211-193e13.5 (15% identical), Drosophila melanogaster rgn (14% identical), Caenorhabditis elegans clec-146 (13% identical), Caenorhabditis elegans clec-196 (12% identical). Paralogues in human: CLEC1A (29% identical), CLEC12B (28% identical), CLEC7A (27% identical), CLEC12A (24% identical), CLEC9A (23% identical), KLRF1 (23% identical), OLR1 (22% identical), KLRK1 (20% identical), KLRC1 (18% identical), KLRC2 (18% identical), KLRD1 (18% identical), KLRC3 (17% identical), and 11 more.
Diseases named in the same sentence as CLEC1B in open-access papers:
CLEC1B is named in the same sentence as 89 diseases in open-access papers, as found by Europe PMC text mining. Sharing a sentence is not in itself a finding about the gene and the disease. The quoted sentences say what the papers report.
thrombosis (18 papers, 2015 to 2025). "Most previous studies on CLEC1B have focused on its association with thrombosis, blood-lymphatic/vascular separation, and tumor metastasis." (PMID 37308868, 2023). "Noteworthy, sCLEC-2 emerges as a pivotal regulator of atherosclerotic thrombosis, whereas human CLEC-2, encoded by CLEC1B, functions as a non-classical C-type lectin receptor." (PMID 40419934, 2025).
Sepsis (14 papers, 2017 to 2025). Sepsis is defined as life-threatening organ dysfunction caused by a dysregulated host response to infection. "In our sepsis model, we found that the m6A modification level of Clec1b mRNA was significantly increased." (PMID 34395520, 2021).
COVID-19 (10 papers, 2021 to 2025). A disease caused by infection with severe acute respiratory syndrome coronavirus 2. "Eight genes associated with platelet activation and pro-thrombosis were upregulated in COVID-19 patients: MPIG6B, HBB, HPSE, CD40LG, STXBP3, CLEC1B, TFPI and GNAS." (PMID 35477940, 2022). "We found that molecules involved in platelet degranulation (CD9, platelet factor 4 (PF4)), aggregation, and activation [CD9, CLEC1B (also known as CLEC2)] were upregulated dramatically in COVID-19 EVs, while none of these proteins were detectable in EVs from healthy donors." (PMID 35820906, 2022).
gastric cancer (10 papers, 2017 to 2025). A primary or metastatic malignant neoplasm involving the stomach. "Cordycepin treatment effectively reduced the proliferation and migration ability of gastric cancer cells by upregulating CLEC1B." (PMID 34627241, 2021).
hepatocellular carcinoma (8 papers, 2020 to 2026). A malignant tumor that arises from hepatocytes. "In support of this, intertumoral expression levels of KC signature genes, particularly TIMD4 and CLEC1B, were positively associated with the survival rates of hepatocellular carcinoma patients." (PMID 36821387, 2023). "In human hepatocellular carcinoma, C-type lectin domain family 1 member B (CLEC1B) is a novel platelet-related molecule associated with TH (HCC)." (PMID 35082906, 2022). "CLEC1B has been identified as a potential biomarker of hepatocellular carcinoma, but to date there are no data in PDAC." (PMID 33334063, 2020).
viral infections (7 papers, 2019 to 2025). "CLEC1B was also shown to be increased in asymptomatic SARS-CoV-2 adults approximately two weeks after their exposure, suggestive of a role in viral infection recovery." (PMID 37533854, 2023).
breast carcinoma (4 papers, 2021 to 2025). "In addition, although CLEC-2 has been reported to be expressed in certain other tumor types, data from the Human Protein Atlas show no detectable CLEC1B expression in either normal breast tissue or commonly studied human breast cancer cell lines." (PMID 41209555, 2025).
liver cancer (4 papers, 2017 to 2025). An epithelial or non-epithelial malignant neoplasm that arises from the liver. "CLEC1B has been reported to be significantly down-regulated in liver cancer." (PMID 38683466, 2025). "Moreover, previous studies have shown that CLEC1B may act as a tumor suppressor in liver cancer, being involved in the regulation of tumor proliferation and metastasis 24,26." (PMID 41209555, 2025).
cholangiocarcinoma (2 papers, 2023 to 2024). A carcinoma that arises from the intrahepatic biliary tree (intrahepatic cholangiocarcinoma) or from the junction, or adjacent to the junction, of the right and left hepatic ducts (hilar cholangiocarcinoma). "The high expression of CLEC1B, CLEC3B and CLEC11A are closely related to the good survival of cholangiocarcinoma." (PMID 39553729, 2024). "We observed that the mRNA expression of CLEC1B in LIHC, cholangiocarcinoma (CHOL), and lymphoid neoplasm diffuse large B-cell lymphoma (DLBC), was lower than that in the adjacent normal tissues." (PMID 37308868, 2023).
malaria (2 papers, 2020 to 2022). Malaria is a serious and sometimes fatal disease caused by a parasite that commonly infects a certain type of mosquito which feeds on humans. "In response to malaria, however, Clec1b expression strongly differed between vaccinated and unvaccinated mice, while expression of Pdpn was not significantly affected, neither by malaria nor by vaccination." (PMID 35214745, 2022). "In the liver of both vaccinated and unvaccinated mice, Clec1b was expressed at a relatively high level of approximately 86 above normalization and was responsive to both malaria and vaccination." (PMID 35214745, 2022).
bipolar disorder (1 paper, 2024). A disorder of the brain that causes unusual shifts in mood, energy, activity levels and the ability to carry out day-to-day tasks. "The CLEC1B gene was found to be correlated with cognitive function and bipolar disorder in humans." (PMID 39062924, 2024).
dementia (1 paper, 2023). Loss of intellectual abilities interfering with an individual's social and occupational functions. "In that study, however, increased, instead of decreased CSF levels of CLEC1B associated with progression to dementia." (PMID 37085545, 2023).
primary immunodeficiency (1 paper, 2023). "In addition, CLEC1B expression was significantly associated with “primary immunodeficiency”, “leishmania infection”, “hematopoietic cell lineage”, “graft versus host disease”, and “cytokine-cytokine receptor interaction” signaling pathways." (PMID 37308868, 2023).
steatosis (1 paper, 2024). Increased lipid within the cytoplasm of cells. "CD63, C-Type Lectin Domain Family 1 Member B (CLECB1), CD38, MANF, and Gamma-interferon-inducible lysosomal thiol reductase (IFI30) were all associated with steatosis grade in PWS." (PMID 39407757, 2024).
tumor (94 papers, 2010 to 2026). "The expression level of CLEC1B was tightly associated with the infiltration of various immune cells in the HCC tumor microenvironment (TME) and positively correlated with a bulk of immunomodulators." (PMID 37308868, 2023). "CLEC1B, a member of the C-type lectin domain family 1, is mainly related to the thromboses caused by platelet aggregation, platelet-mediated tumor proliferation, and metastasis." (PMID 34950206, 2021). "CLEC1B is a signature gene that has been linked to tumour progression." (PMID 35082906, 2022). "In paired tumor tissues and adjacent normal tissues, the expression of CLEC1B also significantly decreased in various tumors, including LIHC." (PMID 37308868, 2023). "CD44, a putative tumor stem cell marker, was significantly associated with C7, CXCL6, CLEC1B, and GPR182 in Hep3B cells and with C7, CXCL6, CLEC1B, and IL1RL1 in Huh7 cells." (PMID 36307751, 2022). "In our present study, CLEC1B was significantly negatively correlated with the expression of tumor stemness marker CD44, and its expression was significantly reduced under hypoxic culture conditions in Hep3B and Huh7 cells." (PMID 36307751, 2022). "Accumulating evidence suggests that the EMT is strongly linked to tumorigenesis, metastasis, and drug resistance, implying that CLEC1B may play an essential role in tumor onset and development by engaging in the EMT." (PMID 37308868, 2023). "Altogether, the role of CLEC1B in the tumor microenvironment of HCC may be intricate, but it is compelling to focus on its effect on immune cell infiltration." (PMID 37308868, 2023). "Collectively, these data demonstrate that the expression of CLEC1B might play a tumor suppression role in the liver." (PMID 37308868, 2023). "In colon cancer, CLEC1B has been shown to suppress tumor metastasis and platelet aggregation." (PMID 37308868, 2023). "Although CLEC1B has recently been reported to be significantly downregulated in HCC tumours, the role of CLEC1B in HCC remains unclear." (PMID 35082906, 2022). "CLEC1B expression has recently been found to be substantially reduced in HCC tumours." (PMID 35082906, 2022). "Low expression of CLEC1B can significantly promote the growth rate of HCC cells, shorten the tumor doubling time, and aggravate the poor prognosis of patients." (PMID 36307751, 2022). "CLEC1B, GYS2, and CYP2C8 were identified as tumor suppressors for the prognosis, however, EXO1 was determined to be an oncogene." (PMID 34950206, 2021). "Collectively, these findings highlight consistent transcriptional alterations in PBMCs and tumor tissues and suggest that STEAP4, EPC1, and CLEC1B may serve as potential non-invasive biomarkers with diagnostic and prognostic relevance in HCC." (PMID 41909879, 2026). "Integration of PBMC and tumor profiles identified STEAP4, EPC1, CLEC1B, and LCN2 as shared DEGs." (PMID 41909879, 2026). "The activation of tumor-specific CD8 + T cells relies on the cross-presentation of APC antigens, such as DCs or macrophages, suggesting that CLEC1B may affect the antigen cross-presentation of APCs and immune activation." (PMID 37308868, 2023). "We found that the expression of CLEC1B significantly affects the clinical survival outcomes of HCC and may play an immunologic enhancement role in the HCC tumor microenvironment." (PMID 37308868, 2023). "In addition, we also constructed hypoxic cell models in Herp3B and Huh7 cells to verify the expression of genes in the prognostic model and found that C7, CLEC1B, and CXCL6 were not only related to the tumor stemness but also related to hypoxia." (PMID 36307751, 2022). "C-type lectin domain family 1 member B (CLEC1B), a tumor platelet-related molecule secreted by activated platelets in the peri-tumor area, could affect thrombus formation and hematogenous metastasis of tumors through interactions with podoplanin." (PMID 34627241, 2021).
tumor (continued). "Recently, CLEC1B was confirmed to be remarkably downregulated and related to tumor hemorrhage in HCC, indicating that CLEC1B could be served as a potential target for PD-L1/PD1 immunotherapy." (PMID 34627241, 2021).
cancer (61 papers, 2012 to 2025). A tumor composed of atypical neoplastic, often pleomorphic cells that invade other tissues. "Gene Set Enrichment Analysis (GSEA) was conducted to investigate the potential association between cancer hallmarks and CLEC1B expression." (PMID 37308868, 2023). "We next analyzed the expression of CLEC1B in tumors and adjacent normal tissues across multiple cancer types." (PMID 37308868, 2023). "We first assessed the transcriptional expression of CLEC1B in multiple cancer types, and the results showed a clear decrease in CLEC1B expression in most tumors, especially HCC." (PMID 37308868, 2023). "Among the proteins differentially present in cancer vs. control were six common to both local and metastatic PDAC: Up—GDF15, TIMP1, and IL1RL1; Down—CCL22, APP, and CLEC1B." (PMID 33334063, 2020). "Six were common for cancer stage (Up: GDF15, TIMP1, IL1RL1; Down: CCL22, APP, CLEC1B)." (PMID 33334063, 2020).
infection (19 papers, 2010 to 2025). The state of being infected such as from the introduction of a foreign agent such as serum, vaccine, antigenic substance or organism. "Our results also showed that LDPm infection for 24 or 48 h largely inhibited LPS-stimulated NF-κB binding to the CLEC1B promoter in DCs and that this inhibition occurred to similar extents at both time points." (PMID 37125906, 2023). "Validation of the gene expression levels obtained by RNA-seq specific to the HCV group (BIRC5 and SLC22A1), the HBV group (CLEC1B), and the group without infection (FGFR4, HSF1, RNF187, HSP90AB1, and HSPB1) was performed using the real-time PCR technique." (PMID 36557005, 2022).
CLEC1B also shares sentences with these, for which no sentence is quoted: melanoma (15 papers); Thrombocytopenia (10); atherosclerosis (7); bacterial infection (5); colorectal cancer (5); osteosarcoma (5); Stroke (4); Dengue virus infection (3); lung carcinoma (3); pancreatic cancer (3); peritonitis (3); venous thromboembolism (3); acute coronary syndrome (2); acute respiratory distress syndrome (2); Autoimmunity (2); brain tumors (2); cardiovascular disease (2); endotoxemia (2); glioblastoma (2); hematological cancer (2); Immune Thrombocytopenia (2); ischemic stroke (2); mesothelioma (2); Oral Cancer (2); squamous cell carcinoma (2); acute liver failure (1); anaplastic large cell lymphoma (1); anemia (1); Arterial thrombosis (1); autoimmune disease (1).
A further 42 diseases each share a sentence with CLEC1B in 1 paper.